TOP1 (DNA topoisomerase I)
Diseases named in the same sentence as TOP1 in open-access papers (continued):
Sharing a sentence is not in itself a finding about the gene and the disease.
cancer (continued). "Notably, the synergistic effect of TOP1 and BRD4 inhibition is relatively selective for cancer cells, mostly sparing normal cells and highlighting tumor susceptibility to transcriptional defects." (PMID 41155268, 2025). "Furthermore, TOP1 was found to regulate several T cell regulatory genes including CD274 and CD276, which serve as markers of limiting T-cell effector response or anti-cancer immunity." (PMID 39156107, 2024). "The TOP1-cleavage complex (TOP1-cc) stabilized by camptothecin (CPT) is adverse to the normal function of TOP1 but can be degraded by the CRL3-mediated neddylation–UPS pathway, thus eliciting cancer cell tolerance." (PMID 39062453, 2024). "Human TOP1 is the target of several poisons such as camptothecin (CPT) and its derivatives, such as topotecan or irinotecan, which are used to treat a variety of human cancers, including colon, lung, ovarian, and small-cell lung cancer." (PMID 39770084, 2024). "Furthermore, it has been shown that sub-cytotoxic concentrations of Top1 poisons can activate the cGAS/STING pathway and immune gene expression in cancer cells, and this process is mediated by the induction of micronuclei in an R-loop-dependent manner." (PMID 39215193, 2024). "TDP1 is a critical enzyme for TOP1-DPCR and is a promising target for cancer treatment." (PMID 37788708, 2023). "We also assessed 7 cancer cell lines with different CUL4A and B expressions and observed an inverse correlation between CUL4 protein levels and SN38 sensitivity, indicating CUL4 proteins as potential predictive biomarkers for TOP1 inhibitors." (PMID 37353483, 2023). "In further research, palmitic acid was detected to have a significant effect on DNA topoisomerase I without affecting DNA topoisomerase II, which makes palmitic acid a good prospect in the production of anti-cancer drugs." (PMID 36985706, 2023). "Our findings show that anticancer TOP1 poisons, CPT and LMP776, increase micronuclei generation with a mechanism involving R-loop accumulation, leading to activation of the cGAS-STING pathway and immune gene expression in HeLa cancer cells." (PMID 35794238, 2022). "The inhibitor of DNA topoisomerase I, irinotecan (CPT-11), is widely used for several cancer types." (PMID 36303648, 2022). "To date, the first known Top1 inhibitor camptothecin (CPT) and some structurally modified CPT derivatives, such as topotecan, irinotecan, belotecan and 10-hydroxy camptothecin have been applied clinically or in clinical trials for cancer treatment." (PMID 35164276, 2022). "CPT and LMP776 were able to stimulate the transcription of the tested immune genes in wt but not in STING-KO B16 cells, showing that the role of STING in immune gene activation by TOP1 poisons is not restricted to human cancer cells." (PMID 35794238, 2022). "In contrast, the sensitivity of human cancer cells or tumours to FL118 is independent of Top1 expression." (PMID 35604033, 2022). "While there are multiple ways in which cancer cells can become resistant to CPT, a prevalent mechanism of resistance is the mutation of Top1 such that the enzyme can no longer bind or cleave DNA." (PMID 35291312, 2022). "Although difficult to achieve, monitoring changes in cancer cell phenotypes, including the expression of CD133, drug-metabolizing enzymes or drug transporters, Top1, and cell-to-cell communication-related genes, would be very useful for the efficacy of drug treatments of CRC." (PMID 35582377, 2021). "Targeted inhibition of RNR activity in cancer cells defective for RNase H2 might hyper-sensitize them to PARP-trapping drugs, which hamper the repair of TOP1-mediated DNA lesions at sites of single genomic rNMPs." (PMID 32187369, 2020). "Moreover, downregulation of the irinotecan target, the topoisomerase-1 enzyme (Top-1), has also been observed in our SN38 resistant cancer cells." (PMID 32326511, 2020).
cancer (continued). "However, the concentration required for FL118 to show its Top1 inhibition activity is 100 to 1,000 fold higher than the concentration required for FL118 to inhibit both survivin promoter activity and cancer cell growth." (PMID 31439015, 2019). "We found that in each of the cancer cell models, cellular TOP1 levels were very similar irrespective of HMGA2 expression." (PMID 31067275, 2019). "The combination of drugs acting on Top1 and TDP1 can significantly increase the effectiveness of chemotherapy and allow to reduce total toxicity on the organism through reducing the therapeutic dose of these anti-cancer drugs." (PMID 30191738, 2018). "Topoisomerase 1 (TOP1) and tyrosyl DNA phosphodiesterase 2 (TDP2) were among the nucleic acid transcripts of choice due to their role as genomic instability biomarkers and their implication in various cancers and neurologic disorders." (PMID 30555231, 2018). "In an apparent contradiction to the negative attribute of the TOP1 activity to genome stability, the detrimental effect of the TOP1-induced DNA lesions on cell survival has made this enzyme a prime target for cancer therapies to kill fast-growing cancer cells." (PMID 27181710, 2016). "Thus, the delineation of TOP1-related SSB and DSB repair mechanisms is of great importance for identifying drug targets that can selectively affect cancer cell survival." (PMID 26287259, 2015). "Beyond the TOP1 copy-number alterations at the genomic level, there is also frequent over-expression of TOP1 mRNA, Top1 protein or enzyme activity level in various cancer types compared to normal adjacent non-cancerous tissue." (PMID 24400218, 2013). "Based on these non-cancer signals we found that 84% of the tumor samples demonstrated an increased TOP1 gene copy number and 64% had an increased TOP1/CEN-20 ratio compared with the non-affected mucosa." (PMID 24400218, 2013). "The TOP1 and CEN-20 signals from unaffected epithelial mucosa (n = 50) located adjacent to the tumor cells were applied to determine the diploid copy numbers in non-cancer cells." (PMID 24400218, 2013). "We therefore propose that the inhibition of DNA Top1 activity by FL118 does not significantly contribute to its ability to inhibit cancer cell growth and proliferation." (PMID 23029106, 2012). "Similarly, MVP and genes encoding for Type I and Type II topoisomerases, such as TOP1, TOP2A, and TOP2B—known to contribute to cancer chemoresistance—showed the same negative association pattern." (PMID 40806276, 2025). "Our recent studies showed that topotecan, a TOP1 inhibitor, binds to ribosomal protein RPL15, resulting in the induction of ribosomal stress and the secretion of DNA-containing exosomes as DAMPs from cancer cells, which activate STING-dependent antitumor immune responses." (PMID 41276688, 2025). "The differential response we present here between highly malignant human cancer cells and normal mouse cells suggests that targeting transcription and inducing readthrough transcription by BRD4 + TOP1 coinhibition may be particularly effective in transcriptionally addicted malignant cells." (PMID 37831776, 2023). "Notably, in fourteen of the TCGA cancer types that were amenable to our analysis, four exhibited a negative correlation between TOP1 expression levels and RNA content, while only one showed a positive correlation." (PMID 37833256, 2023). "In addition, we show that Top1 poisons can activate both IRF3- and NF-kB-dependent genes, however, they cannot in SCLC cancer cells as the cGAS-STING pathway is markedly impaired likely due to several mechanisms including a drastic reduction of STING and/or cGAS expression." (PMID 35794238, 2022). "In principle, the quantitative detection of the activity of TOP1 from humans or from human pathogens enabled by REEAD provides an attractive platform for screening of new compounds with potential clinical relevance for treatment of e.g., cancer or infectious diseases." (PMID 34452216, 2021).
cancer (continued). "Therefore, novel CPT analogues with low toxicity due to not targeted at Top1 was proposed an important research area with great potential to make a breakthrough for development of the next generation of CPT derivatives for cancer treatment." (PMID 31792297, 2019). "Thus, UCHL3 inhibition may offer a worthy therapeutic opportunity for cancer cells that possess upregulated PDB repair mechanisms, particularly those that exploit this upregulation as a mechanism to resist TOP1 targeting chemotherapy." (PMID 29898404, 2018). "For TOP1 inhibitors that are dependent on DNA replication and transcription rates, our analysis predicted cell lines with slower growth kinetics as inherently more drug-resistant irrespective of cancer lineage." (PMID 25036042, 2014). "We observed that TOP1 non-amplified gains showed a non-significant tendency toward poorer prognosis, which may be attributed to increased expression of other cancer-related genes on 20q (see section 4.2)." (PMID 23577133, 2013). "Since we observe here that perturbed DNA topoisomerase I and II activity can effect fragile site breakage at the RET oncogene, more work should be done to investigate the role of topoisomerase poisons and fragile sites in the formation of secondary PTC tumors and other cancers." (PMID 24040417, 2013). "As such, this mutational process is likely to be important not only in cancers with RER deficiency, but also those with high TOP1 activity and tumours with defects in relevant repair mechanisms, such as enzymes that process TOP1cc6 or non-ligatable TOP1-induced nicks." (PMID 35140396, 2022). "Thus, Top2 may partially perform the Top1 work in cancer cells, which could not be controlled by CPTs." (PMID 33217967, 2020). "Interestingly, some synthesized CPT analogues as drug for cancer treatment can improve efficacy independent of Top1 inhibition with novel mechanism of action by targeting important cancer survival-associated oncogenic proteins and/or by bypassing various treatment-resistant mechanisms." (PMID 31792297, 2019). "Interestingly, our previously published evaluation of Top1 levels in the NCI 60 cancer cell line panel revealed that HCT 116 had one of the highest Top1 levels, about 9-fold higher than the SK-MEL-28 cell line, which had one of the lowest Top1 levels in the panel." (PMID 23284638, 2012). "Finally, we have discussed the rationale behind the synergy between the combination of Top1 poison and PARP inhibitors in cancer chemotherapies, which is independent of the ‘PARP trapping’ phenomenon." (PMID 33981998, 2021). "Therefore, when treating patients with low expression levels or diminished activity of topoisomerase 1, TOP1-ADC might not have sufficient therapeutic efficacy, even when the conjugate is successfully targeted to the cancer cell." (PMID 36015333, 2022).
tumor (159 papers, 1995 to 2026). "But when we surveyed the 14 tumor samples with mutations in the human Top1 C-terminal domain residues 713 to 765, the median for the percentage of mutations at G4 is significantly higher at 1.151, with a minimum of 0 to a maximum of 4.330." (PMID 41009588, 2025). "Given their pivotal role in DNA repair, BRCA1/2 mutations can render tumor cells more susceptible to DNA-damaging agents like exatecan and other TOP1 inhibitors." (PMID 41077566, 2025). "Elegant studies have documented a number of mechanisms utilized by tumor cells to become resistant to TOP1 inhibitors, such as upregulation or mutation of the proteins involved in drug efflux and mutations in the TOP1 protein." (PMID 40805174, 2025). "Our study also unveils that these molecular vulnerabilities linked to tumor-promoting genes can be induced under the Ctrl of a regulatory switch governed by an essential regulator of gene Ctrl, TOP1." (PMID 38959318, 2024). "We then created a prognostic model demonstrating that low levels of NEDD8 and TOP1 expression in tumor tissues are associated with a favorable prognosis (p < 0.01)." (PMID 37689760, 2023). "Tumour subclones with the mutation TOP1, known to encode topoisomerase-1 and the mutation TACSTD2, the encoder for TROP2, were found." (PMID 37631232, 2023). "The involvement of this enzyme in the development of tumor resistance to Top1 inhibitors has been confirmed by studies on Tdp1-deficient human cell lines and mice." (PMID 36615517, 2022). "Antipropulsives, other antineoplastic agents, TOP1 inhibitors, and coxibs are linked to neoplasia and their therapies." (PMID 34381361, 2021). "The accumulation of DNA strand breaks (SSBs and DSBs) by TOP1 inhibition in HR-deficient tumor cells is expected to enhance cytotoxicity." (PMID 26287259, 2015). "All SDHB-mutated tumors were sensitive to camptothecin, and one such tumor was extremely sensitive, supporting a potential role for TOP1 inhibitors in treating metastases." (PMID 24516563, 2014). "Until now the association between Top1 assessed in tumor tissue and irinotecan efficacy has only been investigated retrospectively and with focus on CRC." (PMID 24400218, 2013). "Moreover, cetuximab’s inhibition of DNA topoisomerase I has been implicated in the disruption of DNA replication in tumor cells, further contributing to its antitumor efficacy." (PMID 40777125, 2025). "Moreover, the representative confocal images of tumor tissues demonstrated that the loss of TOP1 induced an increase of γH2AX levels but a decrease of BRCA1 levels, consistent with the observation in CC cells." (PMID 39156107, 2024). "However, the antitumor effect exerted by the combination of ATR inhibitor with topoisomerase (TOP1) inhibitor and the subsequent mechanisms underlying enhanced tumor immunogenicity in SCLC remain poorly understood." (PMID 35957613, 2023). "The upregulation of TOP1 is associated with the proliferation of tumor cells." (PMID 35041720, 2022). "The number of mutations for the combined N-Ter, Linker and Core and for the combined C-Ter and Stop was also higher than the 8,194 samples comprising the five types of tumor with the greatest number of TOP1 mutations (p-values of 0.000 and 8.4E-11, respectively)." (PMID 35291312, 2022). "Acquired resistance can be multifaceted because a patient’s tumor may have developed multidrug resistance through ABCG2 or through mutation of TOP1." (PMID 33196706, 2020). "Together, these data show that TOP1 inhibitors potently suppress expression of proinflammatory cytokines, a feature that may contribute to the increased infection risk occurring in tumor patients treated with these agents." (PMID 31242600, 2019). "High Top1 mRNA expression was significantly associated with aggressive clinicopathological features including high histological grade, larger tumor size, high risk Nottingham prognostic index (NPI) > 3.4, Her2 over expression, and ER- and PR- tumors (ps < 0.05)." (PMID 26959889, 2016).
tumor (continued). "The underlying mechanisms of the resistance to Top1-targeting drugs may involve the inappropriate accumulation of drug in the tumor cells, mutations in Top1, or changes in the cellular response to DNA strand breaks." (PMID 23836376, 2013). "Mutations of the TOP1 gene have been observed in tumour cell lines selected for resistance to camptothecin or sometimes in clinical specimens, indicating that amino-acid changes could have consequences on cell response to this drug." (PMID 16983402, 2006). "TOP1 mutations occur in camptothecin-resistant tumour cell lines." (PMID 16983402, 2006). "Consequently,TDP1 activity may be a possible cause of tumor resistanceto TOP1 inhibitors used in the clinic." (PMID 41541557, 2025). "TDP1 activity may be a possible cause of tumor resistance to TOP1 inhibitors." (PMID 34768766, 2021). "Although clinical data using MYC status as a biomarker to guide TOP1 inhibitor therapy are still limited, preclinical evidence supports that MYC‐overexpressing tumours display increased sensitivity to TOP1 inhibitors." (PMID 41537447, 2026). "TOP1, a key modulator of R‐loops and DNA topology, was shown to prevent the accumulation of aberrant R‐loops in MYC‐driven tumours; TOP1 inhibition in this context induces excessive R‐loop formation and ultimately SL." (PMID 41537447, 2026). "Tyrosyl-DNA phosphodiesterase 1 (TDP1) is an important DNA repair enzyme and its functioning is considered as one of the possible reasons for tumor resistance to topoisomerase 1 (TOP1) poisons such as topotecan." (PMID 41155491, 2025). "CRLX101 exhibits prolonged circulation time and preferential tumor accumulation, offering improved safety compared to conventional TOP1 inhibitors such as topotecan and irinotecan." (PMID 41145467, 2025). "Essential genes include CD71 and TOP1, which play a central role in maintaining tumor cell survival and proliferation." (PMID 40046734, 2025). "Here this group proposes a dose-escalation strategy integrating tumor-targeted TOP1 inhibitor with optimized PARP inhibitor scheduling, and evaluate the safety and efficacy in a phase 1 trial of 24 patients with advanced solid tumors." (PMID 41145467, 2025). "Emerging evidence has shown that concurrent inhibition of Ataxia telangiectasia and Rad3-related protein (ATR) and DNA topoisomerase I (TOP1) can result in durable tumor regression in SCLC characterized by high replication stress." (PMID 39103941, 2024). "Consistently, analysis of the GEPIA databases also indicated upregulation of TOP1 mRNA levels in tumor tissues compared to normal controls." (PMID 39156107, 2024). "Comparisons to the standard of care TOP1 inhibitor irinotecan revealed that LMP400 resulted in tumor regression in fewer PDX models, suggesting a potential therapeutic liability of this class of agents in this disease." (PMID 39512899, 2024). "In summary, these findings suggest that TOP1 plays a crucial role in regulating tumor-promoting inflammation as well as PD-L1 production in CC." (PMID 39156107, 2024). "Compared with the control group, tumor volumes and weights were markedly decreased in the TOP1 knockdown group." (PMID 39156107, 2024). "These CPT-11 prodrugs appear to accumulate in brain tumors, have long intra-tumoral half-lives, and slowly release their CPT-11 cargo within the tumor to be converted to the potent TOP1 inhibitor, SN-38." (PMID 38898077, 2024). "Subsequent knockdown studies were performed in vitro and in vivo to evaluate the influence of TOP1 on tumor growth, DNA repair, and inflammatory responses." (PMID 39156107, 2024). "Genotoxic chemotherapies, including TOP1 inhibitors, have been shown to upregulate tumor PD-L1 expression and confer clinical benefits when combined with ICIs." (PMID 38564022, 2024). "Tumor‐intrinsic genomic instability can be further enhanced by TOP1 inhibitors, such as SN‐38, the payload of SG, to instigate immune responses via T cell activation." (PMID 39206932, 2024).